NORAD (non-coding RNA activated by DNA damage)
Diseases named in the same sentence as NORAD in open-access papers (continued):
Sharing a sentence is not in itself a finding about the gene and the disease.
cancer (continued). "NORAD has been confirmed to be overexpressed in various cancers, and it is involved in proliferation, differentiation, and apoptosis." (PMID 33413642, 2021). "Several miRNAs such as miR-199a-3p, miR-608, miR−155−5p, miR-590-3p, miR-495-3p, miR-608, miR-202-5p, miR-125a-3p, miR-144-3p, miR−202−5p, and miR-30a-5p have been recognized as targets of NORAD in different cancer cell lines." (PMID 34485302, 2021). "Based on these researches, aberrantly upregulated NORAD was identified in several human cancers and affect the development of cancers." (PMID 34551785, 2021). "Collectively, NORAD in an oncogenic lncRNA in most tissues and a possible target for inventions against cancer." (PMID 34485302, 2021). "For example, MALAT1, HOTAIR and NORAD in cancer cells can elicit effective cancer inhibitory effect." (PMID 29220444, 2017). "NORAD also exhibits cancer type-specific roles in bone metastasis." (PMID 40872531, 2025). "NORAD behaves as an oncogene in many human cancers, where it is upregulated." (PMID 38791575, 2024). "LINC00657 (NORAD) upregulation as a result of DNA damage in cancer is a common finding." (PMID 38087258, 2023). "Next, we asked how NORAD expression levels correlated with cancer patients’ outcome." (PMID 37680988, 2023). "Interestingly, ZFAS1 was negatively correlated with ZEB2, while NORAD was positively correlated with ZEB2 in PRAD cancer type." (PMID 36514044, 2022). "It remains to be determined how the altered levels of NORAD, observed across multiple cancer types, might affect PUM‐dependent processes and tumorigenesis." (PMID 34668345, 2022). "In endometrial cancer, NORAD orchestrates cancer progression by acting as a tumor suppressor." (PMID 34969360, 2022). "It appears that NORAD is a critical regulator of miRNAs in different cancers." (PMID 35773731, 2022). "Bioinformatics analysis by ENCORI1 found that lncRNA NORAD binds with RBP FUS in cancer cells." (PMID 34307380, 2021). "Besides, lncRNA NORAD also exerts decoy function by sequestering target proteins to regulate genomic stability or cancer metastasis." (PMID 34307380, 2021). "In addition, NORAD has interactions with cancer-related pathways, particularly STAT, TGF-β, Akt/mTOR, and PI3K/AKT pathway." (PMID 34485302, 2021). "Therefore, in addition its role in the initiation of cancer possibly through influencing genomic stability, NORAD partakes in the progression of cancer through enhancement of EMT." (PMID 34485302, 2021). "Numerous studies have evaluated the role of NORAD in the development of cancer." (PMID 34485302, 2021). "In addition, NORAD has interactions with cancer-related pathways such as STAT, TGF-β, Akt/mTOR, and PI3K/AKT pathway." (PMID 34485302, 2021). "Several studies demonstrated that NORAD could act as a ceRNA to sponge miRNAs and ultimately regulate the expression of several factors that play vital roles in cancer progression." (PMID 34771549, 2021). "Furthermore, NORAD and miR-433-3p was correlated with overall survival and cancer-specific survival." (PMID 33462197, 2021). "Collectively, NORAD is a prospective marker and target for combating cancer." (PMID 34485302, 2021). "In addition, NORAD has a role in the modulation of response of cancer cells to a number of chemotherapeutic drugs such as doxorubicin and cisplatin." (PMID 34485302, 2021). "In this type of cancer, importin β1 has been found to be a binding partner of NORAD." (PMID 34485302, 2021). "NORAD was identified as an oncogene in pancreatic and ovarian cancer, while its roles in lung and breast cancers have been controversial, indicating a context-dependent role in cancer progression." (PMID 32555178, 2020). "The mechanisms of NORAD in cancers are complex, which include many factors and signaling pathways." (PMID 32267831, 2020). "Increasing studies demonstrated that NORAD played its role in cancers via acting as a ceRNA." (PMID 32694945, 2020). "Increased studies revealed that NORAD expression was elevated in various cancers." (PMID 32694945, 2020).
cancer (continued). "The abnormal expression of NORAD was connected with the advancement of various cancers." (PMID 32694945, 2020). "Previous studies had demonstrated that NORAD played important roles in various types of cancer." (PMID 33292272, 2020). "NORAD may have effects on cell proliferation, invasion, and apoptosis in cancer cells and is related to the development of cancers." (PMID 32267831, 2020). "We further evaluated the regulatory effects of downregulated of NORAD, specifically whether the knockdown of miR‐205 affected cancer cell migration and invasion." (PMID 30843652, 2019). "Interestingly, NORAD could regulate cancer progression by acting as competing endogenous RNAs to modulate miRNA expression and function." (PMID 38791575, 2024). "Similarly, the expression of the NORAD was notably increased in cancer tissues and cells compared with that in normal tissues and cells in NSCLC, which regulates the proliferation, migration, and invasion capabilities of NSCLC cells by targeting the miR-520a-3p/PI3k/Akt/mTOR signaling pathways." (PMID 36793900, 2023). "To further explore the involvement of the DDR proteins in the NORAD-mediated accumulation of γH2Ax we used siRNAs to KD two of the hits identified in the NORAD-associated proteome (LC-MS/MS experiment), namely PARP1 and CDK1, both proteins being extensively linked to cancer and DXR response." (PMID 37680988, 2023). "In present study, bioinformatics prediction revealed that NORAD could interact with several miRNAs, and we selected miR-30a-5p for further investigations owing to its role in the regulation of cell behaviors in several types of cancers." (PMID 33292272, 2020). "LncRNAs such as NORAD and MALAT1 play significant roles in the progression of cancer to bone metastasis." (PMID 40872531, 2025). "Three well-known upstream long non-coding-RNAs (lncRNAs); MALAT1, NORAD, and NEAT1 target miR-202 and inhibit its tumor suppressive function thus fueling cancer progression." (PMID 35682549, 2022). "Moreover, we observed a negative correlation between the XBP1s/u ratio and the Delta Ct values of lncRNAs NORAD, NEAT1, and LINC00299, representing their gene expression levels in cancer tissues." (PMID 37706018, 2023). "Notably, a specific group of lncRNAs named hypoxia-responsive lncRNAs (HRLs) can be modulated by hypoxic tumor microenvironment, such as NORAD, RAB11B-AS1, and AC020978, are involved in cancer progression." (PMID 35110544, 2022). "Due to the critical role of NORAD in the maintenance of genome stability and cell cycle progression, it is not surprising that dysregulation of this lncRNA leads to cancer." (PMID 34485302, 2021). "Ablation of NORAD using a duplex RNA approach lead to the hyperactivity of PUMILIO genes and to chromosomal instability augmenting the sensibility of NORAD depleted cells to anti-cancer agents." (PMID 29732012, 2018). "This study found that NORAD was activated due to an increase in oxidative stress, and this lncRNA upregulated ATG5 and ATG12 levels and may be regarded as a useful biomarker in this cancer to predict oxaliplatin resistance." (PMID 36983973, 2023). "NORAD levels were also consistently higher in cancer stroma than in PC regions, regardless of site." (PMID 35317841, 2022). "NORAD might serve as a ceRNA of miR-541-3p to promote PKM2 expression, thereby enhancing the development of bone metastasis in PCa by promoting internalization and transfer of EVs of cancer cells, providing an insight into a novel treatment for the disorder." (PMID 33722248, 2021). "Many of the well-studied lncRNAs, that are considered as regulatory molecules with various significant functions in cancer, have no junctions in their sequences such as MALAT1, NKILA, NEAT1 and NORAD." (PMID 34202021, 2021). "The regulatory networks controlled by NORAD and HCG11, though showing a set of genes that is not big enough to result in significant functional enrichment, indicate that essential processes in cancer signaling are present." (PMID 33739352, 2021).
tumor (53 papers, 2016 to 2025). "Some studies have reported that high expression of NORAD is associated with high histological grade, larger tumor size, and advanced clinical stage of BRCA21." (PMID 37993524, 2023). "NORAD expression was considerably decreased in BC samples, and its deficiency was linked with poor tumor tissue development." (PMID 35756601, 2022). "Down-regulation of NORAD has been associated with poor patients’ outcome, advanced tumor size and TNM stage." (PMID 34485302, 2021). "Considering that radiation led to severe DNA damage in cells and NORAD knockdown increased genomic instability upon DNA damage, we reasoned that NORAD knockdown increased the tumour mutation burden (TMB) in ESCC upon radiation." (PMID 34587992, 2021). "More precisely, our findings suggest that shorter DSS and DFI in BRCA patients are associated with increased NORAD expression, suggesting that NORAD may be involved in tumor growth, metastasis and resistance to treatment in patients with BRCA malignancies." (PMID 37993524, 2023). "Conversely, NORAD is upregulated in OS tissues, repressing miR-155-5p and promoting tumor progression." (PMID 40128298, 2025). "Immunohistochemistry analysis of xenografts’ tumor sections confirmed that in vivo NORAD inhibition results in increased miR-323a-3p and p-PERK and decreased PUM1 levels." (PMID 38339387, 2024). "Due to NORAD’s extended range of interacting partners, there has been contradictory data on its oncogenic or tumor suppressor roles in BC." (PMID 38339387, 2024). "Our study underscores the role of lncRNA NORAD in promoting tumor malignancy and modulating energy homeostasis." (PMID 39215037, 2024). "In contrast, the control group and the group receiving EVs with si-lncRNA NORAD exhibited a reversal of the tumor growth acceleration induced by M2 macrophage-derived EVs." (PMID 39215037, 2024). "The yes-associated protein (YAP)/WW domain containing the transcription regulator 1 (TAZ)–TEA domain transcription factor (TEAD) complex is shown to be inversely correlated with NORAD expression in breast-invasive carcinoma in TCGA." (PMID 38339387, 2024). "Considering the complexity of the NORAD network, NORAD appears to have a dual effect depending on the tumor type." (PMID 37680988, 2023). "To assess the functional implications of NORAD in tumor cells, we conducted the cellular functional analysis using CancerSEA." (PMID 37993524, 2023). "NORAD actively engages in a multitude of biological processes within the tumor microenvironment, with a notable impact on cellular migration and invasion." (PMID 38066437, 2023). "Altogether, BMSC-EVs promoted tumor growth by carrying NORAD to regulate the miR-877-3p/CREBBP axis." (PMID 35281474, 2022). "On the other hand, expressions of NORAD and CREBBP were augmented while miR-877-3p was diminished in tumor tissues of nude mice administered with EVs, which was abrogated by administration of EVs by silencing NORAD." (PMID 35281474, 2022). "We analyzed the associations among nine lncRNAs (NEAT1, XIST, NORAD, MALAT1, MIR29B2CHG, LINC00943, AC005332.4, AC092718.4, and LINC01146), risk score, tumor purity, and immune cell infiltration." (PMID 35756601, 2022). "It was revealed that NORAD functioned as a tumor promoter to sponge miR-577 thus elevating TPM4 in OSCC, which indicated that NORAD was worthy to be studied as a target for the treatment of OSCC." (PMID 34991683, 2022). "In conclusion, the data from our studies revealed that NORAD was a tumor promoter and it accelerated the progression of OSCC by targeting miR-577/TPM4 axis." (PMID 34991683, 2022). "In vivo experiments validated that BMSC-EV-derived NORAD facilitated tumor growth by upregulating CREBBP via miR-877-3p." (PMID 35281474, 2022). "NORAD knockdown cells displayed elevated PD-L1 protein expression, and IHC staining of xenograft tumours showed that tumours derived from NORAD knockdown cells exhibited stronger PD-L1 staining than tumours derived from control cells." (PMID 34587992, 2021).
tumor (continued). "NORAD enhances the proliferation, tumor growth, metastasis, and doxorubicin resistance, though it restricts apoptosis and autophagy." (PMID 33718173, 2021). "Apart from this study, other in vivo studies have shown the role of NORAD in enhancement of tumor progression in animal models." (PMID 34485302, 2021). "IHC staining of xenograft tumours showed that tumours derived from NORAD knockdown cells exhibited less EEPD1 staining." (PMID 34587992, 2021). "Chromosomal abnormalities are present in approximately 60%-80% of human tumors, and NORAD is vital in maintaining chromosomal stability and normal mitosis in human bodies, which further highlights the role of NORAD in regulating tumor development." (PMID 33722248, 2021). "Over-expression of NORAD has been related with poor clinical outcome of patients with diverse types of neoplasms." (PMID 34485302, 2021). "The estimated tumor volume result indicated that NORAD knockdown can significantly inhibit the cell tolerance to oxaliplatin." (PMID 33462197, 2021). "On the other hand, over-expression of FUBP1-binding fragment of NORAD has attenuated tumor growth in this model." (PMID 34485302, 2021). "Additional rescue experiments suggested that overexpressing NORAD or IL-33 markedly reversed the anti-tumor role of miR-496 in GC." (PMID 34895039, 2021). "In contrast, CDDP induced significant regression in tumours derived from KYSE30/CDDP-R cells pretreated with sh-NORAD beginning in the 4th week, indicating that NORAD knockdown partly reversed CDDP resistance." (PMID 34893064, 2021). "The xenograft tumour volumes of KYSE30 cells with NORAD overexpression were significantly larger than those of KYSE30 cells pretreated with the EV." (PMID 34893064, 2021). "Our results found that the methylation levels at the NORAD promoter were enhanced in tumor tissues compared with those in normal tissues and gradually increased with the progression of EC." (PMID 32555178, 2020). "The expression levels of NORAD in PC tumor tissues and adjacent normal tissues obtained from 45 PC patients were determined by qRT-PCR, and the expression level of NORAD in the tumor tissues group was remarkably higher than the normal group." (PMID 33292272, 2020). "In our study, we analyzed the public data in TCGA and collected the tumor tissues of EC patients, which illustrated that NORAD was downregulated due to promoter hypermethylation in EC patients compared with normal tissues." (PMID 32555178, 2020). "Taken together, our results demonstrated that both endogenous and exogenous NORAD expression promoted EC cell apoptosis as a tumor suppressor." (PMID 32555178, 2020). "We first analyzed the RNA-seq data of 544 EC tissues and 23 normal endometrial tissues in The Cancer Genome Atlas (TCGA) and found that the expression level of NORAD was lower in tumor tissues than that in normal tissues." (PMID 32555178, 2020). "Our findings provide mechanistic insight into the critical roles of NORAD as a tumor suppressor in EC progression." (PMID 32555178, 2020). "The expression of RAB11A was decreased in the tumor tissues with injection of PC-3 cells transfected with NORAD siRNA, and miR-30a-5p inhibitor weakened this result." (PMID 33292272, 2020). "NORAD was found to be functioned as a ceRNA to bind and downregulated miR-30a-5p that was downregulated in PC tumor tissues." (PMID 33292272, 2020). "The results showed that the mice with NORAD siRNA infected cells significantly inhibited tumor volume and tumor weight, while miR-30a-5p inhibitor obviously decreased the suppressive effect of NORAD on the tumor growth." (PMID 33292272, 2020). "In conclusion, these data supported that NORAD play a role in promoting in vivo tumor growth by suppressing the expression of miR-30a-5p." (PMID 33292272, 2020). "Lastly, tumorigenicity assay in vivo demonstrated that NORAD increased tumor volume and weight via miR-30a-5p /RAB11A pathway." (PMID 33292272, 2020).